BRF1 (BRF1 general transcription factor IIIB subunit)
Diseases named in the same sentence as BRF1 in open-access papers (continued):
Sharing a sentence is not in itself a finding about the gene and the disease.
tumor (16 papers, 2010 to 2024). "It is important to note, however, that in these studies, the effect of the tumor BRF1 mutations on Pol III activity and on synthesis of various Pol III transcripts was not examined." (PMID 32611613, 2020). "Fourth, we can use alcohol not only to naturally induce HCC tumorigenesis in mice to study the role of Brf1 in the occurrence of HCC but also to study the role of Brf1 in the development of HCC after tumor formation." (PMID 39308682, 2024). "Studies have shown that BRF1 is highly expressed in human tumor tissues of HCC patients, and inhibiting its expression can suppress HCC development." (PMID 39749197, 2024). "In contrast, repressing Brf1 decreases the activity of these genes and inhibits cell proliferation and tumor development." (PMID 33995823, 2021). "Upregulation of Pol III genes would serve to enhance the protein biosynthesis to promote cell proliferation and transformation and tumor development and growth, while Brf1 alteration in cells directly affects the products of tRNAs and 5S rRNA genes." (PMID 33995823, 2021). "The result indicates that a strong signal of Brf1 was detected in tumor foci tissue, while a very weak reaction of Brf1 with its antibody was observed in paracarcinoma tissue." (PMID 33995823, 2021). "The quantitation of the immunoblot results of these samples indicates that the cellular levels of Brf1 and pAMPKα in tumor tissues are significantly higher than those in corresponding ANT samples." (PMID 33995823, 2021). "Our earlier studies have demonstrated that alcohol increases Brf1 expression in tissue culture and animal models, which facilitates cell proliferation and transformation, and tumor formation." (PMID 33995823, 2021). "For the first time, we demonstrate that elevated BRF1 expression in the prostatic epithelium can impact upon the tumour microenvironment in vivo." (PMID 31740786, 2020). "The immunohistochemistry stain of Brf1 of human HCC samples shows that Brf1 is overexpressed in tumor foci (middle), compared to paracarcinoma tissue of human HCC (left)." (PMID 32685086, 2020). "In clinical PCa cBioPortal data, alterations in BRF1 and C7 significantly co-occurred when interrogating all (p = 0.002) and metastatic (p < 0.0001) tumour cases in MSKCC (2010) dataset." (PMID 31740786, 2020). "Brf1 expression is enhanced in tumor tissues of mouse HCC with alcohol feeding, compared to those nontumor liver tissues, such as the liver tissues with or without alcohol intake." (PMID 32685086, 2020). "Our early studies have demonstrated that Brf1 was overexpressed in tumor foci of human HCC cases, compared to paracarcinoma tissue of HCC." (PMID 32685086, 2020). "This indicates that alcohol-increased Brf1 expression is critically important in cell transformation and tumor development." (PMID 31781337, 2019). "Emerging evidences have indicated that alcohol induces deregulation of Brf1 and Pol III genes to cause the alterations of cell phenotypes and tumor formation." (PMID 31781337, 2019). "The results indicate that the levels of ERα or Brf1 protein in HBC tumor foci are higher than those in ANT." (PMID 28972307, 2017). "Strong Brf1 signals are observed in tumor foci of the HBC tissue compared to the para tissue (around tumor foci; Fig. 1A1,B1)." (PMID 28972307, 2017). "Univariate Cox proportional hazard regression analysis showed that Brf1 expression (P<0.001), tumor diameter (P=0.007), recurrence (P=0.003), serum AFP (P=0.011) and TNM stages (P<0.001) were significantly associated with overall survival." (PMID 26701855, 2016). "We analyzed the RNA-seq and tumor progression data from “Liver Hepatocellular Carcinoma (TCGA, provisional)” at cBioPortal and found that high expression of BRF1 predicts a poor overall survival (20.6 versus 53.3 months, P=0.032)." (PMID 26701855, 2016).
tumor (continued). "In this study, biopsies of human HCC, liver tumor samples of mice and cell lines of normal and tumor liver were utilized to determine the alteration of Brf1 expression using cytological and molecular biological approaches." (PMID 26701855, 2016). "This indicates that the change of Brf1 levels in the cells results in alteration of alcohol-promoted phenotypes of non-tumor liver cells." (PMID 26701855, 2016). "Inhibition of Brf1 expression reduced anchorage-independent colonies to form and promoted tumor formation in mouse." (PMID 25400119, 2014). "Apoptosis was more robust in tumor tissue from the Brf1 knockdown group." (PMID 39308682, 2024). "Interestingly, whilst high BRF1 protein levels were observed in all PtenΔ/ΔBRF1Tg tumours, some tumours from PtenΔ/Δ mice also had elevated BRF1 expression." (PMID 31740786, 2020). "Brf1 expression is elevated in HCC tumor tissues of animals and humans." (PMID 32685086, 2020). "Our studies demonstrate that Brf1 expression is elevated in HCC tumor tissues of mice and humans." (PMID 32685086, 2020). "Upregulation of Brf1 (TFIIB-related factor 1) and Pol III gene (RNA polymerase III-dependent gene, such as tRNAs and 5S rRNA) activities is associated with cell transformation and tumor development." (PMID 32685086, 2020). "Brf1 expression is elevated in the human tumor tissue of HCC." (PMID 32685086, 2020). "Our studies have revealed that Brf1 is highly expressed in human tumor tissues of HCC cases." (PMID 32685086, 2020). "Brf1 specifically regulates transcription of tRNAs and 5S rRNA genes, while the deregulation of the Pol III genes is tightly linked to cell transformation and tumor development." (PMID 31781337, 2019). "We hypothesised that Brf1 heterozygous mice would show suppression of tumour initiation and development." (PMID 30858608, 2019). "The levels of Brf1 in tumor foci are much higher than those of ANT." (PMID 28972307, 2017). "The results show that both ERα and Brf1 have positive staining in ER+ tumor tissues." (PMID 28972307, 2017). "Liver tumor cell lines show high levels of Brf1 protein and mRNA, compared to non-tumor cell lines." (PMID 26701855, 2016). "The present studies indicate higher level of Brf1 in human tumor tissue of HCC." (PMID 26701855, 2016). "Interestingly, ERα and Brf1 are colocalized in the nuclei of the tumor cells." (PMID 28972307, 2017). "Furthermore, the induction of Brf1 expression caused by ethanol in tumor lines is significantly higher than in non-tumor line." (PMID 26701855, 2016). "However, little is known about the role of alcohol in Brf1 and Pol III gene (RNA polymerase III-dependent gene) transcription, which is responsible for protein synthesis and tightly linked to cell transformation and tumor development." (PMID 26701855, 2016). "Our results showed that downregulation of Brf1 inhibited HCC cell growth and clone formation, as well as subcutaneous tumor growth in mice." (PMID 39308682, 2024). "Downregulation of Brf1 slowed HCC cell proliferation, colony growth, and mouse subcutaneous tumor growth and increased the sensitivity of HCC cells to apoptosis induced by chemotherapy drugs." (PMID 39308682, 2024). "The biological functions of Brf1 and Pol III genes are responsible for protein synthesis, whereas protein synthesis is essential for tumor cell growth." (PMID 33995823, 2021). "The studies of ours and others have demonstrated that decreasing the expression of Brf1 and Pol III genes represses cell proliferation, cell transformation, and xerograph tumor growth." (PMID 33995823, 2021). "Our studies have demonstrated that alcohol increases Brf1 expression and Pol III gene transcription to facilitate cell transformation and tumor formation." (PMID 28972307, 2017). "A decrease in Brf1 expression reduces Pol III gene transcription and is sufficient for repressing cell transformation and xenograft tumor formation." (PMID 28972307, 2017).
tumor (continued). "The results reveal that the levels of Brf1 mRNA and protein in tumor cell lines [TSCML (tumor stem cells of mouse liver) and HepG2-ADH], are higher than the non-tumor line (AML-12), an immortalized liver cell line of mouse." (PMID 26701855, 2016). "Our studies indicate that enhancement of Brf1 and Pol III gene expression is correlated with tumor formation in alcohol-fed mice." (PMID 25400119, 2014). "Brf1 and products of Pol III genes are elevated in both transformed and tumor cells suggesting that they play a crucial role in tumorigenesis." (PMID 25400119, 2014). "Recently, the overexpression of another Pol III transcription factor BRF1 has been shown to increase Pol III-mediated transcription, resulting in the transformation of cells in vitro and tumor formation in vivo." (PMID 20668658, 2010). "Similarly, downregulation of Brf1 inhibited HCC proliferation, colony growth and subcutaneous tumor growth in mice." (PMID 39308682, 2024). "Similarly, the TATA box-binding protein human Maf1 and the oncogene Ras can promote the transcription of tRNAs by targeting RNA pol III, particularly the Brf1 subunit of TFIII B factor, thereby promoting tumor progression." (PMID 34975491, 2021). "We implicate a non-cell autonomous role for high Brf1 expression in the prostatic epithelium as impacting on the tumour microenvironment with altered immune infiltrates." (PMID 31740786, 2020). "Heterozygous loss of Brf1 did not alter tumor development or tumor number or size, suggesting that Brf1 is not limiting for intestinal tumorigenesis." (PMID 30858608, 2019). "The difference in Brf1 expression between tumor foci and adjacent noncancerous tissue (ANT) is marked." (PMID 28972307, 2017). "The results indicate that there is not a significant correlation between Brf1 expression and other clinicopathological features, such as patient age, pausimenia, histological type, clinical stage, tumor size, lymph node, and metastasis." (PMID 28972307, 2017). "More interestingly, the cellular level of Brf1 mRNA in HCC tissues of alcohol-fed NS5A mice is also significantly higher than in the non-tumor liver tissues of these mice with or without alcohol intake." (PMID 26701855, 2016). "Furthermore, our studies demonstrate that the amounts of Brf1 and Pol III gene expression in tumor liver cell lines is significantly higher than non-tumor liver cell line." (PMID 26701855, 2016). "However, there are some observations that suggest that BRF1 is a tumor suppressor rather than a protein whose increased expression favors cancer." (PMID 32611613, 2020). "The most clinically pathological characteristic of 218 cases is not the significant correlation between Brf1 expression and other clinic pathological features, such as patient age, pausimenia, histological type, clinical stage, tumor size, lymph node, and metastasis." (PMID 31781337, 2019). "We found that tumours from KPC Brf1fl/fl mice showed a lack of recombination at the Brf1 locus." (PMID 30858608, 2019). "Therefore, we further determined the cellular levels of Brf1 in tumor and non-tumor liver cell lines in these systems." (PMID 26701855, 2016).
infection (3 papers, 2023 to 2025). The state of being infected such as from the introduction of a foreign agent such as serum, vaccine, antigenic substance or organism. "Our finding that CPSF30 was recruited to B2 SINE loci in a Brf1-dependent manner suggests that infection stimulates polyadenylation of B2 SINE ncRNAs in association with their Pol III transcription." (PMID 40768347, 2025). "Like B2 SINE genes, CPSF30 ChIP-seq coverage at tRNAs was both MHV68 infection-induced and dependent on Brf1." (PMID 40768347, 2025). "Among the proteins identified on the screen, ZFP36L1 (also known as TIS11B or BRF1) was consistently upregulated already at 6 hours post-infection." (PMID 37830871, 2023). "Here, we show one example of an HSV-1 viral protein (ICP0) that has been previously linked to ERK activity during infection, activates ERK signaling, increases Brf1 protein levels, and enhances B2 SINE and pre-tRNA transcription upon transfection in murine fibroblasts." (PMID 36752632, 2023).
prostate (2 papers, 2020 to 2024). "In conclusion, our data highlight that elevated BRF1 expression promotes prostate carcinogenesis." (PMID 31740786, 2020).
BRF1 also shares sentences with these, for which no sentence is quoted: gastric cancer (2 papers); Intellectual disability (2); leukemia (2); 3-M syndrome (1); acromelic dysplasia (1); breast adenocarcinoma (1); central nervous system cancer (1); Cerebellar hypoplasia (1); dental anomaly (1); esophageal cancer (1); Floating-Harbor syndrome (1); head and neck squamous cell carcinoma (1); melanoma (1); Mowat-Wilson syndrome (1); pancreatic tumour (1); pontocerebellar hypoplasia (1); rectal tumors (1); spinocerebellar ataxia type 17 (1); Ververi-Brady syndrome (1); viral infection (1); X-linked mental retardation syndrome (1).